WDR89 (WD repeat domain 89)
Synonyms: C14orf150; MSTP050; MGC9907
Tractability: PROTAC: ubiquitination databases record sites on it; its protein half-life has been measured.
Gene: Protein-coding gene on chromosome 14 (63,597,039 to 63,642,080, reverse strand). Ensembl gene ENSG00000140006.
Subcellular location (Human Protein Atlas): Cytosol; Intermediate filaments
Genetic constraint (gnomAD): Loss-of-function variants: 17 observed, 28.13 expected, observed/expected ratio (o/e) 0.6, 90% interval 0.41 to 0.91. The upper end of that interval is the gene's LOEUF score, 0.91, which puts it in group 3 of 6, group 1 being the genes least tolerant of losing a copy. Missense variants: 396 observed, 475.6 expected, observed/expected ratio (o/e) 0.83, 90% interval 0.77 to 0.9. Synonymous variants: 138 observed, 165.12 expected, observed/expected ratio (o/e) 0.84, 90% interval 0.73 to 0.96.
Homologues: Orthologues: chimpanzee WDR89 (99% identical), macaque WDR89 (96% identical), dog WDR89 (87% identical), pig WDR89 (85% identical), rat Wdr89 (82% identical), mouse Wdr89 (81% identical), guinea pig WDR89 (78% identical), tropical clawed frog wdr89 (55% identical), zebrafish wdr89 (41% identical), Drosophila melanogaster CG12134 (26% identical).
Diseases named in the same sentence as WDR89 in open-access papers:
WDR89 is named in the same sentence as 4 diseases in open-access papers, as found by Europe PMC text mining. Sharing a sentence is not in itself a finding about the gene and the disease. The quoted sentences say what the papers report.
brain tumor (2 papers, 2021 to 2025). "Additionally, WDR89 has been observed to be overexpressed in adamantinomatous craniopharyngioma (ACP), the most common primary brain tumor in the sellar region among children." (PMID 39906820, 2025). "In the GSE60815 and GSE94349 databases, expression profile analysis suggested that compared with the normal brain group (including pituitary) and most other primary pediatric and adult brain tumors (including MEN, GNCT, MPNST, RMS, PA), WDR89 was highly expressed in ACPs." (PMID 34966342, 2021).
COVID-19 (1 paper, 2024). A disease caused by infection with severe acute respiratory syndrome coronavirus 2. "We found novel significant associations with MRAS and WDR89 in gene-based analyses, and constructed a polygenic risk score that explained 1.01% of the variance in severe COVID-19." (PMID 38517939, 2024).
WDR89 also shares sentences with these, for which no sentence is quoted: Adamantinomatous Craniopharyngioma (1 paper); Usher syndrome type 1B (1).